HIF1A (hypoxia inducible factor 1 subunit alpha)
Diseases named in the same sentence as HIF1A in open-access papers (continued):
Sharing a sentence is not in itself a finding about the gene and the disease.
melanoma (continued). "Moreover, the presence of elevated levels of HIF-1α in advanced melanomas may suggest its involvement in melanoma progression at local levels." (PMID 35158770, 2022). "Also in melanoma, Sdc3 expression is induced by hypoxia-inducible factors such as HIF1α." (PMID 35628603, 2022). "Additionally, these results were validated in the non-melanoma cell line Hep3B, even though a weak upregulation could be observed in the luciferase experiments upon HIF-1α overexpression." (PMID 34035373, 2021). "Loss of sensitivity to IFN treatment as a result of HIF-1α/RIG-I (retinoic acid-inducible gene I)-dependent downregulation of IFNαR (interferon α receptor) expression and consequent diminished NK- and CTL-mediated cell death was also observed in human and murine melanoma cells." (PMID 33918883, 2021). "Moreover, in vitro studies indicated that the melanogenesis process induced in melanoma cells may, in fact, be a trigger for an increase in HIF1-α expression." (PMID 33352824, 2020). "Additionally, under normoxia, melanoma cells can regulate and stabilize HIF-1α at the translational level, through mTOR and melanoma antigen-11 (MAGE11), that is involved in the inhibition of prolyl hydroxylase domain protein 2 (PHD2), a HIF-1α negative regulator." (PMID 32528879, 2020). "Moreover, it has been suggested that HIF1-α may interact with the TET2 protein in the melanoma and glioblastoma cell lines." (PMID 33352824, 2020). "Additionally, a previous study has demonstrated that Bcl-2 overexpressing melanoma cells, under low oxygen conditions, induce the HIF-1α cascades through modulation of nuclear factor κB (NF-κB) and other transcription factors to induce transcriptional activation of VEGF." (PMID 32859045, 2020). "Melanoma cells could stabilize HIF-1α by downregulation of VHL46." (PMID 30804329, 2019). "Therefore, by demonstrating that CXCR7 is capable of accelerating HIF-1α translation by promoting Src-mediated eIF4E phosphorylation, our findings raise the possibility of interfering with this axis as clinical therapeutics for melanoma patients." (PMID 30804329, 2019). "Thus, miRNA-138/HIF1α is a potential target for the clinical diagnosis and treatment of melanoma." (PMID 31371307, 2019). "Moreover, ROS also drive the stable expression of HIF-1α to activate the Met protooncogene, which facilitates the proliferation of the extracellular matrix, angiogenesis, and the proliferation and metastasis of melanoma cells." (PMID 31636809, 2019). "Thus, CXCR7 supports melanoma angiogenesis through enhancing HIF-1α-mediated secretion of VEGF." (PMID 30804329, 2019). "However, HIF-1α or HIF-2α independently contributed to melanoma metastasis." (PMID 30575721, 2018). "However, the protein expression level of HIF-1α in the IHT group was significantly lower than that in the IH group (P < 0.05), suggesting that tempol treatment attenuates the OSA-like IH-induced expression of HIF-1α in this melanoma lung metastasis mouse model." (PMID 29433520, 2018). "Furthermore, to mimic an aggressive melanoma microenvironment triggered by the “angiogenic switch”, the constitutive expression of HIF-1α in melanoma cells was enhanced by the chemically induced stabilization of this transcription factor, after incubation with cobalt chloride." (PMID 30138430, 2018). "In addition, we already know that melanoma cell exposure to extracellular acidosis deeply inhibits HIF1α expression, leaving tumor cells to acquire an OxPhos phenotype, probably under the influence of the increased SOX2 expression, and able to maximize energy efficiency with the available resources." (PMID 30466459, 2018).
melanoma (continued). "Since our previous studies reported that HIF-1α is a molecular target for SIM cytotoxicity in B16.F10 murine melanoma cells we investigated whether the lipophilic statin could improve the antitumor efficacy of an anti-angiogenic agent, DMXAA, when these drugs were co-administered." (PMID 30138430, 2018). "Furthermore, constitutive HIF1α activity has been described in malignant melanoma." (PMID 28595656, 2017). "However, M3 melanoma cells are a melanin-producing cell line, and both control cells and methyl sulfone-treated cells produce equal amounts of melanin, negating potential differentiating effects of melanin on HIF-1α levels." (PMID 26536104, 2015). "Therefore we investigated whether AA and A2P decreased HIF-1α protein in WM9 metastatic melanoma cells through acting on PHD." (PMID 26547841, 2015). "The significant differences in HIF-1α expression between nevi and melanomas were consistent with the data of an immunoblot analysis of cell lysates obtained from cultured HEMs, the radial growth phase melanoma cell line WM983-A, and various metastatic melanoma cell lines." (PMID 23043612, 2012). "Conversely, stabilized HIF-1α, in conjunction with PI3K/AKT activation, enhances Notch signaling in melanoma." (PMID 40399946, 2025). "The same trend holds for VEGF and HIF1a, where these genes are expressed with the expected range of values compared to historical melanoma cases with WT BRAF, but significantly higher in melanoma with BRAF V600E genotype." (PMID 40869231, 2025). "Clinical studies consistently demonstrate that elevated HIF-1α expression correlates with increased VEGF expression, microvascular density, and poor prognosis in melanoma patients, underscoring its role as both a biomarker and therapeutic target." (PMID 41463281, 2025). "Meanwhile, epigenetically silencing of Hif1α via H3K27me3 in the promoter region was achieved by CRISPR/dCas9-EZH2 system, and the Hif1α silenced TAMs manifested as inheritable M1 phenotype in melanoma." (PMID 40375990, 2025). "In malignant melanoma, FBXO22 increases tumor cell invasiveness and angiogenesis through the HIF-1α and VEGF pathways." (PMID 40534867, 2025). "In this study, we employed an integrated, multi-scale approach to investigate how melanoma CSCs respond to siRNA-mediated silencing of three key regulatory genes: KLF4, SHH, and HIF1α." (PMID 40854961, 2025). "Replacing the codon of HIF1A abolished the melanoma cells’ dependence on U34 enzymes and induced drug resistance in BRAFV600E melanoma." (PMID 41465101, 2025). "Under hypoxia, endothelin-1 synthesis is induced, sustaining HIF-1α/2α-driven VEGF-A and VEGF-C expression in tumor cells and ECs, thereby promoting angiogenesis and melanoma cell migration." (PMID 40399946, 2025). "GAB2, found to be amplified in 30.6% of acral melanomas and 17.1% of mucosal melanomas, has been shown to induce tumour angiogenesis by regulating hypoxia inducible factor 1 subunit alpha (HIF‐1α) and VEGF expressions in NRAS‐driven melanoma." (PMID 39757723, 2025). "In the present study, the silencing of HIF1α, SHH, and KLF4 in melanoma CSCs resulted in marked alterations in cell morphology, cytoskeletal organization, and molecular profile." (PMID 40854961, 2025). "BNIP3 deficiency induces NCOA4-mediated ferritinophagy, with PHD2-mediated HIF-1α downregulation inhibiting tumor glycolysis and growth in BNIP3-silenced melanoma cells." (PMID 41298345, 2025). "Integrin α5β1 activation in melanoma cells highly expressing CD271 triggers the MAPK/ERK pathway, which activates STAT and HIF1α pathways." (PMID 40399946, 2025). "HIF-1α regulates melanoma VEGF expression, and increasing evidence supports the HIF-1α/VEGF axis contributes to metastasis and EMT." (PMID 38426087, 2024). "In melanoma cell lines, BMAL1 activities were found to oppose those of HIF-1α and promote oxidative phosphorylation." (PMID 38426087, 2024).
melanoma (continued). "Relatively uniform evidence backs up the immune-evasion and metastatic nature of melanoma-intrinsic HIF-1α signaling, but additional research is required to understand the context(s) altering HIF-1α function in T cell and NK cell biology." (PMID 38426087, 2024). "Inhibiting the transcriptional activities of HIF-1α increases NK cells and CTLs mediated by CCL2- and CCL5 in the tumor bed in a murine melanoma model, thus enhancing the anticancer effects of peptide vaccine and anti-PD-1 blocking antibodies." (PMID 38165484, 2024). "HIF-1α, in particular, orchestrates responses to hypoxia, including the upregulation of the melanocyte-specific transcription factor MITF, promoting melanoma growth." (PMID 39611156, 2024). "Previous studies have highlighted that HIF-1α can affect the progression of melanoma through the PI3K/AKT/mTOR signaling pathway, and celastrol has been demonstrated to inhibit the growth of melanoma cells by inhibiting PI3K/AKT signaling." (PMID 38771435, 2024). "Other transcriptional factors involved in PD-L1 regulation in melanoma include MYC, hypoxia-inducible factor-1α and 2α (HIF-1α/2α), STAT3 and NF-κB." (PMID 38633217, 2024). "To determine which HDAC effectively regulates HIF-1α expression, we treated melanoma cell lines, SKMEL-2 and SKMEL-28, with different HDAC inhibitors and examined the changes in HIF-1α expression levels." (PMID 36831463, 2023). "Our results show that the HDAC8i PCI-30451 effectively suppresses HIF-1α, demonstrating it to be a novel indirect inhibitor of HIF-1α in melanoma." (PMID 36831463, 2023). "Of note, the activation of PI3K/AKT signaling in melanoma cells has been reported to induce PHD2 inhibition, thereby promoting HIF-1α stability." (PMID 37175841, 2023). "It has been demonstrated that HIF1-α can bind to the HRE motif of the promoter of PD-L1 gene and induce its expression in prostate, breast, and lung cancer as well as melanoma." (PMID 37443821, 2023). "Previous studies reported that in melanoma, PARP1 interacts with the C-terminal domain of HIF-1a and regulates the expression of HIF-1a." (PMID 37821935, 2023). "In patients with melanoma, HDAC8 and HIF1A expressions show a positive correlation and the elevated expression of these genes is associated with poor prognosis." (PMID 36831463, 2023). "Lastly, we corroborated our results with samples from patients with melanoma, which showed that the upregulation of HDAC8 and HIF-1α is correlated with poor prognosis in melanoma." (PMID 36831463, 2023). "Regarding the melanoma stage, both HIF-1a and HIF-2a presented statistically significant higher levels in the patients with advanced melanoma, while the HIF-1a/HIF-2a ratio significantly decreased in patients with high melanoma stages." (PMID 36294785, 2022). "Very recently, we demonstrated that suppression of the transcriptional activity of HIF-1α resulted in an increased infiltration of NK cells and CD8+ T cells in the tumor microenvironment of melanoma." (PMID 35211123, 2022). "Briefly, HIF-1α binds directly to the HRE motif in the promoter of PD-L1 gene and induces its expression in various cancer cells such as melanoma, lung, breast, and prostate cancer." (PMID 35795658, 2022). "Its overexpression in UACC-257 melanoma cells increases cell growth, BrdU positive cells, γ-H2AX levels, normoxic HIF-1α expression, and decreased p27Kip1 expression." (PMID 35326089, 2022). "Our study showed high levels of hypoxia-inducible factor-1a (HIF-1a) and hypoxia-inducible factor-2a (HIF-2a) in the melanoma patients." (PMID 36294785, 2022). "In our study, HIF-1a and HIF-2a presented high levels in melanoma patients compared with the control group." (PMID 36294785, 2022). "Recent studies revealed that HIF1α can be induced by different signaling pathways, such as PI3K/Akt/mTOR, RAS/RAF/MEK/ERK, JAK/STAT, and NF-κB pathways controlling melanoma tumor growth, metabolism, motility, and apoptosis evasion." (PMID 35163570, 2022).
melanoma (continued). "Xanthomicrol, a flavone extracted from Dracocephalum kotschyi Boiss leaf, showed an antiangiogeneic effect in mice melanoma (B16F10) model (50 mg/kg) through negatively regulating the expression of VEGF, HIF-1α, and p-Akt." (PMID 35784750, 2022). "PI3Kγ induces metastasis through increasing the formation of PDGF-BB and improving the expression of MMP-9, uPA, VEGF, HIF-1α, and HIF-2α in PDAC and melanoma, respectively." (PMID 32902664, 2021). "In this study, we evaluated in vivo the impact of suppressing the transcriptional activity of HIF-1α, by deleting the domain responsible for its dimerization with HIF-1β, on the infiltration of major cytotoxic immune cells into B16-F10 melanoma." (PMID 34155342, 2021). "Ku80 was a potential molecular target for melanoma treatment and regulated anti-tumor role of melatonin by targeting and activating PDK1 in HIF1A-dependent manner." (PMID 33962616, 2021). "HIF-1α is one of the targets of miR-138 and miR-138 negatively regulates HIF-1α to suppress proliferation, invasion and migration in melanoma and ovarian cancer." (PMID 33673181, 2021). "Silencing of HIF-1α and HIF-2α was found to completely inhibit melanoma capillary-like structure formation, indicating that vasculogenic mimicry in melanoma cells is controlled by HIF-dependent transcriptional mechanism." (PMID 33964953, 2021). "In non-melanoma cancers, hypoxia activates TGF-β signaling, which then cooperates with HIF1α to promote invasion." (PMID 34604096, 2021). "The levels of HIF-1α and CAIX proteins under hypoxia were decreased in melanoma cells exposed to vemurafenib in a cell type-dependent manner, thus indicating hypoxia involvement in the response to drug treatment and in the induction of heterogeneity." (PMID 33964953, 2021). "Our results revealed that suppression of the transcriptional activity of HIF-1α induced the infiltration of NK cells and CD8+ T cells in the tumor microenvironment of melanoma." (PMID 34155342, 2021). "In melanoma, MAPK and PI3K pathway activation induces glycolysis and its decoupling from the TCA cycle via stimulation of hypoxia-inducible factor 1α (HIF1α) and the v-MYC avian myelocytomatosis viral oncogene homolog (MYC)." (PMID 33498757, 2021). "Physiologically, HIF1α inhibition repressed IL-9 induction in Th9 cells and subsequently promoted the tumor development in B16-OVA melanoma tumor model." (PMID 34075041, 2021). "At the transcriptional level, MITF controls genes involved in cell survival (BCL2, HIF1A, BCL2A1), migration (DIAPH1, MET) and proliferation (CDK2, TBX2, CDKN1B), providing important signals for growth of melanoma cells." (PMID 34289891, 2021). "HuR-NP treatment significantly diminished protein expression of HuR, Cyclin D1, Cyclin E1, BCL-2, HIF1-α, VEGEF-A, and an increased expression of p27 at both 24 h and 48 h in melanoma cell lines (p < 0.05)." (PMID 33418925, 2021). "Recent studies suggest that HIF1α is regulated by STAT3 as the later increases the half-life of the transcription factor in both human and mouse melanoma cells." (PMID 32211322, 2020). "The role of this pathway in regulating tumor growth and angiogenesis, via induction of HIF-1α and VEGF expression, is well-defined in melanoma and other cancer cell types." (PMID 33424993, 2020). "In human melanoma, there is a positive correlation between the VM formation and the ischemic group and the expression of HIF-1a, and HIF-1a expression is positively correlated with VEGF expression." (PMID 32169087, 2020). "To this end, we first established BRD4 knockout A375 melanoma and A2780 OC cells using the CRISPR/Cas9 system and exposed these cells and the control cells to normoxia (20% O2) or hypoxia (1% O2) to induce HIF1α protein for 24 h." (PMID 32286255, 2020). "The in vitro and in vivo results in this study showed that Huaier decreased the expression of HIF-1α and VEGF in melanoma tissues." (PMID 32596377, 2020).
melanoma (continued). "Increased expression of HIF-1α is correlated with VEGF upregulation and critical for melanoma progression." (PMID 30804329, 2019). "Intriguingly, early studies reported that melanoma cells could accumulate HIF-1α under normoxic conditions, while this event is regulated in response to CXCR7 alterations, suggesting that CXCR7 is implicated in the abnormal expression of HIF-1α and hypoxic responses in melanoma." (PMID 30804329, 2019). "Mouse melanoma xenograft model treated with AQP1 siRNA demonstrated decreased microvessel density and increased CASP3 and HIF-1α expression." (PMID 31013775, 2019). "Overall, our findings first time suggests that HIF‐1α/VEGF signaling‐mediated EMT and angiogenesis is critically involved in anti‐metastasis effect of luteolin as a potential therapeutic candidate for melanoma." (PMID 30653763, 2019). "Increased glucose uptake in BrafV600E; Phd2−/− melanoma cells was significantly inhibited by FM19G11 treatment, a HIF inhibitor or HIF-1α knockdown, which is accompanied by concomitant decreased Glut1 expression." (PMID 30575721, 2018). "The aim of our study was to investigate the inhibition of murine melanoma growth by combining two agents: anti-vascular - DMXAA and the HIF-1α inhibitor - digoxin and explaining the mechanism of action of this combination." (PMID 29743548, 2018). "Hence, we evaluated whether LPS modulates HIF1α expression in B16 melanoma cells." (PMID 28662055, 2017). "Rh123low (Low Rhodamine 123) cells exhibit stem-like phenotype correlate with enhanced levels of HIF1α, Oct4 and ABCB5 and reduced level of Cyclin D1 and CDK4 which define the quiescent and chemoresistance properties of CSCs in melanoma." (PMID 28137308, 2017). "This is consistent with our previous observation showing the reduction of OS and DFS of patients with a pigmented melanomas at stage 3 and 4, and on expression of several vitamin D related pathways such as VDR, CYP24A1 and CYP27B1 and HIF-1α." (PMID 27542227, 2016). "In melanoma, ASS1 transcription is primarily governed by c-Myc (a positive regulator) and HIF-1α (a negative regulator) and is inducible in parental cells in arginine depleted conditions." (PMID 26771234, 2016). "Elevated c-Myc overwhelms HIF-1α to bind E-box (enhancer box) in ASS1 promoter, and collaborates with transcription factor SP4 binding to GC box to initiate ASS1 transcription in melanoma cells." (PMID 26771234, 2016). "Accumulation of HIF-1α and HIF-2α was measured via immunohistochemistry in 46 patient samples of nodular cutaneous malignant melanomas." (PMID 26547841, 2015). "In our initial experiments, we tested the ability of physiological concentrations of ascorbic acid (AA) to decrease the amount of HIF-1α protein in a human melanoma cell line (WM1366), isolated from a vertical growth phase melanoma." (PMID 26547841, 2015). "The expression of HIF1α and CAIX in a 518A2 melanoma xenograft model was evaluated by immunohistochemistry." (PMID 25997619, 2015). "In our study, we first found that up-regulation of IGFBP5 decreased HIF1α expression and the other IGFBPs family members, IGFBP2, IGFBP4, IGFBP6, and IGFBP7 to some extent in melanoma cells." (PMID 26010068, 2015). "The next step will be pre-clinical investigations of AA/A2P and HIF-1α/HIF activity in animal models that most closely recapitulate the initiation and progression of human melanoma." (PMID 26547841, 2015). "The expression of HIF1α, the master regulator of tumorigenesis, tumor metastasis, and development, increased with the activation of ERK1/2-MAPK pathway in human melanoma." (PMID 26010068, 2015). "Selenite supplementation decreases the ROS load in cancer cells, with corresponding inhibitory effects on HIF1α, VEGF, and lung metastasis of murine melanoma cells." (PMID 26000250, 2015). "Under normoxic conditions, HIF1α can be stabilized by various growth factors, cytokines and oncogenes, as shown for BRAFV600E in melanoma." (PMID 26000250, 2015).